CD4 (CD4 molecule)
Diseases named in the same sentence as CD4 in open-access papers (continued):
Sharing a sentence is not in itself a finding about the gene and the disease.
infection (continued). "Depletion of CD4+ T cells in severe infections signifies the immune system’s inability to mediate antibody and CD8+ T cell responses, effector cell differentiation, and tissue repair." (PMID 37457959, 2023). "Previous studies have reported that reduced CCR5 expression protects CD4 + T cells from infection by the R5 tropic virus impairing viral entry and replication thus impeding HIV progression." (PMID 37231494, 2023). "Protecting CD4+ CAR T cells from infection will likely increase the potency of the CAR T cell product." (PMID 36680242, 2023). "Whereas most of HIV-infected CD4+ T cells die within a few days of infection, in vitro studies suggest that HIV-1-infected macrophages developed mechanisms to limit cell death, resulting in viral replication for extended periods of time." (PMID 36988579, 2023). "In the Med LN, at all time points following infection, the numbers of total cells, and numbers of Ifnγ+, CD4, and CD8 T cells were increased compared to naïve animals." (PMID 37842651, 2023). "Tr1 and Th1 CD4 T cells were highly transcriptionally active during infection, while T-regs and Tfr were the least activated." (PMID 37968278, 2023). "HIV establishes 2 forms of infection: either CD4+ T cells are infected productively and thus produce infectious virions, or cells are infected latently and thus produce none or few HIV transcripts and proteins." (PMID 38420260, 2023). "Virus-specific memory T cells that develop following infection or immunization can be rapidly recalled during re-infection to aid antibody production (helper CD4+ T cells), and directly kill virus-infected cells (cytotoxic CD8+ T cells)." (PMID 36969244, 2023). "DC can contribute to the viral reservoir through de novo viral production from cis-infected DC or trans-infection of CD4+ T cells through immunological synapses formed during antigen presentation or exosomes carrying infectious virions." (PMID 38045254, 2023). "All vaccination groups displayed significantly higher levels of IFN-γ+ CD4+ T cells (over 15-fold) than the naïve infection group." (PMID 37515025, 2023). "Only a small portion of CD4+ T cells resided in the spleen tissue, and the other portion of CD4+ T cells reached the infection site or other organisms in the blood circulation and played a role in anti-E. multilocularis infection." (PMID 38151996, 2023). "This is in contrast to other studies finding that CD4+ T cells are necessary and sufficient to both clear infection, and prevent reinfection." (PMID 38441219, 2023). "Here, we demonstrate that fusion of infected CD4+ T lymphocytes with human macrophages leads to their efficient and productive infection." (PMID 36988579, 2023). "The study will enrol 57 HIV-infected adults that have started antiretroviral therapy at the early stage of infection with undetectable viremia (for a year) and ≥450 CD4+ T cells/mL (for 6 months) that will undergo treatment interruption." (PMID 36678440, 2023). "A study from Spain reported the most severe mpox infection in the PLHIV with poor disease control (CD4 = 265), than in the other individuals with HIV-MPXV." (PMID 37754280, 2023). "While there was a lower number of total CD4+ Tregs at Day 30 after infection in the mice that received Tregs from CS-exposed mice, this was not statistically significant." (PMID 37965256, 2023). "At 12 h and 144 h post-infection, a higher percentage of CD4+ CD25+ and CD4+ CD25+ Foxp3 cells were observed in the HLA-A11/DR1 Tg group." (PMID 38035330, 2023). "Age at diagnosis, smoking, baseline SCr > 5.74 mg/dL, CD4+ T-cell count < 281/μL, and intravenous CYC therapy are risk factors for infection." (PMID 36755215, 2023). "Activated CD4+ T cells then migrate from secondary lymphoid organs to the infected sites, where they participate in controlling the infection." (PMID 38004749, 2023).
infection (continued). "Transient blockade of IL‐27 elicits high levels of unique CD127+ and KLRG1+ memory CD4+ T cells, elevates antibody production, and enhances protective immunity against secondary infection." (PMID 37855243, 2023). "It is noteworthy that, most CD4+ T cells undergo apoptosis, while the remaining 10% form long-lived memory cells that are responsible for the immune response upon secondary infection." (PMID 38004749, 2023). "The infection of primary CD4+ cells with isogenic viruses HIV-1 Luc (Vpr +/−) further confirmed the involvement of virion-encoded Vpr in ciTRAN induction." (PMID 37672576, 2023). "The main reason is that gut dysfunction and severe depletion of CD4+ T-cells are intricately associated in HIV/SIV infections, as they occur almost simultaneously early in infection." (PMID 36813761, 2023). "CD4+ T cells found in the BALs of these mice had a Th2-type phenotype and secreted IL-13 during infection." (PMID 37896776, 2023). "Ultimately, our data demonstrate that infection with LD generates an Ag+ CD4 T cell immunity that displays a less exhausted status associated with stronger functional fitness and most likely provides better help to CD8 T cells." (PMID 36883950, 2023). "There was a significant (p < 0.05) increase in frequency of Rora-expressing CD4+ T cells in lung of primary infected mice, compared with uninfected mice, with a further significant (p < 0.001) increase after secondary infection." (PMID 37387671, 2023). "IL-6 deficiency results in reduced Tfh differentiation and antibody-mediated immunity, a process in part dependent on IL-6 signaling on CD4 T cells to sustain Tfh formation and function at the later stages of infection." (PMID 37583704, 2023). "Of note, 51.1% of patients mounted detectable SARS-CoV-2-specific CD4+ T cell responses during the first week of infection, and 37.7% of patients mounted detectable SARS-CoV-2-specific CD8+ T cell responses during the first week of infection." (PMID 37225706, 2023). "Attempts to resolve the specific characteristics and effector mechanisms of cytotoxic CD4+ T cells have revealed variation between humans and mouse models and between infection and cancer contexts." (PMID 37161048, 2023). "This conclusion is consistent with the preferential infection in vivo of memory CD4+ T cells that co-express CD4 and ⍺4β7." (PMID 38064524, 2023). "Conversely, the homologous BBIBP-CorV booster group showed the same levels of CD4 counts but substantially lower CD8 counts after breakthrough infection." (PMID 38140668, 2023). "Accordingly, CD4+ T cell-depleted VillinCre_STAT6vt mice had significantly lower fecal egg counts than CD4+ T cell-depleted STAT6vt mice on day 14 after secondary infection." (PMID 37018382, 2023). "The SARS CoV-2 antibody and CD4+ T cell responses induced by natural infection and/or vaccination decline over time and cross-recognize other viral variants at different levels." (PMID 37575243, 2023). "During a later stage of infection (14 dpi), the percentage of CD4+ cDC2 began to increase again in spleens of C57BL/6 mice." (PMID 38201217, 2023). "We found that resting memory CD4 + T cells co-cultured with IEC had significantly higher infection rates than resting memory CD4 + T cells cultured alone." (PMID 37202790, 2023). "The barrier to a cure for HIV-1/AIDS is the population of infected CD4+ T memory cells that establish proviral latency during early infection." (PMID 37515158, 2023). "As anticipated from results above, a greater frequency of CD4+ T cells responded to cGAMP activation following infection with P. falciparum, supporting increased sensitivity of parasite-specific CD4+ T cells to STING activation." (PMID 37781920, 2023). "Using multicolor flow cytometric analysis, we first characterized the kinetics of IL-17RB, the cognate receptor for IL-25 expression on lung CD4+ T helper cells during pulmonary C. neoformans H99 infection for 3, 7, and 14 days." (PMID 37337050, 2023).
infection (continued). "In contrast, mature vaginal LCs efficiently transmitted HIV-1 to CD4 T cells, resulting in infection levels of ~ 47.3% in CD4 T cells after co-culture." (PMID 36841916, 2023). "In pregnant mice, challenge infection resulted in 29%–31% contraction of CD4+Tnv subset, and 84%–128% and up to 36% expansion of CD4+ Tem and Tcm subsets, respectively, the maximal response being noted in vaccinated/infected pregnant mice (p < 0.01–0.001)." (PMID 38104118, 2023). "While the CD4+ T cell expression of Timp1 was thought to explain the delayed migration of CD4 compared to CD8+ T cells into the brain parenchyma, infection of Timp1−/− mice surprisingly showed increased CD4+ T cell retention in the perivascular space." (PMID 38140641, 2023). "Kinetics of infection in activated CD4+ T and HaCaT cells (human keratinocytes) were similar, although viral yields were lower (log10 PFU/mL = 6.40 vs. 4.12 at 48 hpi, P < 0.001)." (PMID 37079384, 2023). "We next specifically depleted CD4+ T cells with antibody and found that this reduced infection-induced LCM expansion and LCM RELMα expression." (PMID 36948193, 2023). "We infused untreated CD4+ T cells infected with HIV ex vivo into mice 9 days after PBMC inoculation to ensure an established infection prior to onset of GVHD." (PMID 36680242, 2023). "For example, interferon response was a common signature identified in multiple studies, including in vitro infection, in vivo responses of activated CD4+ T cells, and total CD4+ T cells obtained from viremic people with HIV." (PMID 37111397, 2023). "At four weeks post infection, co-transfer of Fo B with CD4+ T cells resulted in ~10-fold increase in splenic Brucella loads compared to animals transferred CD4+ T cells alone, demonstrating Fo B inhibit CD4+ T cell responses following B. melitensis infection." (PMID 37721965, 2023). "Within splenocytes, expression of IFNγ, TNFα, IL17, IL13, IL10, and TGFβ were changed by both infection and vaccination within CD4 and CD8 T cells and regulatory T cells." (PMID 36799886, 2023). "The results were more explanatory when studies on patients with HIV with higher CD4+ cell counts were observed to lack severe mpox infection development." (PMID 37631913, 2023). "The robust increase in CD8+ T-cells and more modest increase in CD4+ T-cells in the liver is consistent with our depletion data showing a greater role of CD8+ T-cells in control of the infection." (PMID 37866114, 2023). "In BALB/c mice, the cell glucanase Crf1 from A. fumigatus was found to induce memory CD4+ Th1 cells and cross-protection against lethal infection with C. albicans." (PMID 37367569, 2023). "We show herein how directly establishing HIV-producing and latently infected cells through infection of resting CD4+ T cells creates a mechanism to continually replenish both populations not only in Fiebig I, but also at any stage of infection." (PMID 37733443, 2023). "In summary, CD4 and CD8+ T cells work in tandem to combat EBV, with the CD8+ response being more heavily implicated in controlling infection." (PMID 38179040, 2023). "Even though the time until disease or death is the most direct measure of virulence of any infection, the CD4+ T cell decline is commonly used as a surrogate measure." (PMID 37161335, 2023). "The proportion of CD4+ T cells decreased at 24 h of infection, increased on 3 d and then decreased again on 7 d, while the trend of CD8+ T cells was exactly the opposite." (PMID 37587524, 2023). "This reflects the extraordinary ability of CD4+ T cells to differentiate into distinct effector subsets that co-operate with other immune cells to protect the host against infection with specific pathogens." (PMID 37116791, 2023). "Survivors from VARV infections had low levels of circulating CD4+ T cells responding to VACV antigen stimulation up to more than 40 years after infection." (PMID 36986285, 2023).
infection (continued). "Active infection of the endocervix with CT results in a local accumulation of CD4+ T cells that express the HIV co-receptors." (PMID 37766360, 2023). "In our case, we showed that the novel QTAP-mRNA vaccine elicits predominantly CD4 T cell response during the early phases of infection whereas the late phase of infection is characterized by both CD4 and CD8 T cell response in vaccinated mice." (PMID 37359562, 2023). "Increased CD4+ cells in the lungs of MFD-fed mice during acute and chronic stages of infection likely caused the elevated levels of IFNγ and initiated host survival mechanisms." (PMID 36676177, 2023). "It is important to consider that following SARS-CoV-2 infection, the number of Tregs (CD3+ CD4+ CD25+) considerably decreased throughout the development of infection and symptoms." (PMID 36992283, 2023). "Initially, the expression of Blimp1, T-bet and Bcl6 transcriptional factors was evaluated in CD4+ T cells from B6 and P2rx7-/- mice at the acute phase of infection." (PMID 36993971, 2023). "The CD4+/CD8+ ratio was similar to that demonstrated after MSC administration during early infection." (PMID 37175761, 2023). "Here, leukocytes, specifically CD4+ T cells, upregulate Bhlhe40 expression in the spleen and liver in response to infection with P. yoelii." (PMID 37843306, 2023). "Our second model (10-day) implemented direct infection of resting CD4+ T cells via cell-to-cell virus transmission from the autologous infected, activated CD4+ T cells." (PMID 38156317, 2023). "By 21 days post-infection, individual birds variably became highly biased toward one or the other subset, as is expected from the development of clonal CD4+ T cell tumors." (PMID 36992316, 2023). "The acute phase is also mediated by CD8+ T-cell responses in the early stages of infection, whereas CD4+ T-cell responses are present in the later stages of infection." (PMID 37014125, 2023). "Gonzalo-Gil and colleagues have previously showed that CD4 + T cells from HIV controllers are resistant to infection with the R5 tropic HIV and that this phenotype is reversed by introducing CCR5." (PMID 37231494, 2023). "This is due to the activities of mainly peptide-specific CD8+ T and CD4+ T helper cells acquired from previous infections." (PMID 37219610, 2023). "Infection terminates in the death of the host cell; thus, infection invariably leads to the depletion of CD4+ T lymphocytes." (PMID 37408185, 2023). "The adoptive transfer of CD4+ T cells into nude mice demonstrated their beneficial role during infection and B cell differentiation as they were necessary to induce the production of RSV-specific antibodies." (PMID 37896776, 2023). "The mean number of individual peptide-specific CD4+ T-cell responses detected before infection was 12.2 (range: 4–20) in these patients." (PMID 37215095, 2023). "During the early acute phase of infection (3 days post-infection), there was a reduction in the frequency and number of CD4+Foxp3+ Tregs in the spleen of CKO mice compared to WT mice." (PMID 37908369, 2023). "CD4 T cells control the acute stage of infection through IFN-γ-mediated activation of macrophages, while CD8 T cells keep infection in the chronic stage under control." (PMID 37900421, 2023). "Then, HDAC6 stabilization by the overexpression of wt-TDP-43 generates a non-permissive state for target cells by impairing MT stabilization and making HIV-1 Env/CD4-mediated pore fusion formation and subsequent viral entry and infection difficult." (PMID 37108826, 2023). "A UMAP analysis revealed that total CD4+ T cells were grouped in 7 clusters and that productive p24+ cells were skewed to given clusters throughout the course of infection." (PMID 38420260, 2023). "We verified that this infection mode of alveolar macrophages was sensitive to pre-incubation with anti-CD4 antibodies." (PMID 36988579, 2023).
infection (continued). "Having shown that expression of GPI-scFv X5 on CEMss trans-restricts HIV-1 in iDCs, we next evaluated if GPI-scFv X5 expression on T cells would also block infection of neighboring untransduced CD4+ T cells." (PMID 37781368, 2023). "It is one of the most highly expressed transcripts in naive CD4+ T cells and has been shown to be downregulated in response to T cell activation and other infections." (PMID 37079384, 2023). "As the amount of CD4 cells decreases due to the infection, GvHD becomes milder, and mice are healthier." (PMID 36680271, 2023). "Yet, human CCHF survivors have displayed memory CD8+ T cells that are detectable several years following infection, and both CD4+ and CD8+ T cells were shown to be important for survival of acute CCHFV infection in a immunocompromised mouse model." (PMID 36933409, 2023). "However, once CD4+ T cell counts exceeded 500 cells/μl, the risk of Bh infection remained at a low and stable level as CD4+ T cell counts increased, the value of the range falls between 0.0 and 1.0, and it gradually approaches 0.0 as CD4+ T cell counts increases." (PMID 37697423, 2023). "There has been no way to identify the subset of Mtb antigen-specific effector CD4 T cells actively responding at the site of infection and learn with an unbiased approach what distinguishes this population phenotypically and functionally." (PMID 38110410, 2023). "The development of mitochondrial dysfunction is one reason to explain the rapid depletion of CD4+ T-lymphocytes in the acute phase of infection." (PMID 37048145, 2023). "The study found that when CD4+ T cell counts exceeded 500 cells/μl, the Bh infection consistently remained at lower levels, which aligns with our experience and understanding." (PMID 37697423, 2023). "Equally pivotal is data showing that despite CD4 T cell depletion during infection, frequencies of CCR5 and CCR7 within the CNS remain relatively stable." (PMID 38060615, 2023). "S-specific TSCM CD4+ cells sharply increased in number during the infection, while M- and N-specific TSCM CD4+ cells showed a slower and less prominent increase." (PMID 38006037, 2023). "We injected uninfected or day 5-infected mice with GP plus adjuvant and analyzed splenic GP66-specific CD4+ T cells by flow cytometry 8 days after immunization (which was 13 days post-infection)." (PMID 36715223, 2023). "CD4+ TRM cells localize at the site of infection and mount a rapid and targeted immune response against bacterial infections." (PMID 37749129, 2023). "Other infection models showed substantial tissue damage because Th1-polarized CD4+ T cells were unable to transform into an IL-10-producing state." (PMID 36679947, 2023). "We also determined the memory phenotype of S-specific CD4+ T cells according to the infection background." (PMID 37575243, 2023). "Although the luminal macrophage removes pathogens through their phagocytic mechanisms, indeed, we noted a high macrophage in BAL fluid, the pathogen that escapes the primary phagocytic process, requires innate CD4 + or CD8 + T-cells to control the infection." (PMID 37700291, 2023). "In mouse models, we have provided: in vivo peptide antigen on TLR-activated APC, IL-2:anti-IL-2 Ab complexes, infection surrogates, and others that have supplied PR signals in humans and all enhance CD4 memory and protection." (PMID 38152398, 2023). "Using a Mann–Whitney–Wilcoxon test, they report a country-specific difference in the CD4+ T cell level after primary infection." (PMID 37161335, 2023). "The second mechanism is called cis-infection, which involves productive infection of DCs and Mø with de novo production of viral particles that infect surrounding CD4+ T lymphocytes." (PMID 37243118, 2023). "Infection of the GIT results in severe CD4+ T cell depletion, immune dysfunction, dysbiosis, and significant structural and functional damage." (PMID 36890518, 2023).